KLF4 (KLF transcription factor 4)
Diseases named in the same sentence as KLF4 in open-access papers (continued):
Sharing a sentence is not in itself a finding about the gene and the disease.
myocardial infarction (7 papers, 2017 to 2025). Gross necrosis of the myocardium, as a result of interruption of the blood supply to the area, as in coronary thrombosis. "This will provide deeper insights into the precise mechanism underlying the inhibitory effect of ischemic postconditioning on the KLF4/NF-κB pathway and explore additional mechanisms associated with myocardial infarction." (PMID 40471885, 2025). "Our investigation demonstrates the potential of IIM in improving myocardial cell apoptosis, inflammation, and autophagy triggered by myocardial infarction through the inhibition of the KLF4/NF-κB pathway in both intracellular and extracellular environments." (PMID 40471885, 2025). "In vivo, miR-10a-overexpressed or KLF4-downregulated old hBM-MSCs were implanted into infarcted mouse hearts after myocardial infarction (MI)." (PMID 29848383, 2018). "Strong nuclear Klf4 expression with clear region specific differences was detectable in porcine and human heart samples after myocardial infarction." (PMID 28977827, 2017). "Transcription factor binding site analysis suggested a strong role for Kruppel like factor 4 (Klf4) in the regulation of gene expression following myocardial infarction, and was therefore investigated further by immunohistochemistry." (PMID 28977827, 2017). "Similar regulation of nuclear Klf4 expression was observed in human heart samples after myocardial infarction with a mean percentage of Klf4 positive cells (±SD) of 72%±10.0% in the BZ and 7%±4.5% in the IZ (P-value < 0.001)." (PMID 28977827, 2017). "Our study presents compelling evidence suggesting a significant increase in KLF4 expression in H9C2 cells subjected to H/R treatment, indicating its potential role as a pro-inflammatory mediator in myocardial infarction." (PMID 40471885, 2025).
Nephropathy (7 papers, 2015 to 2025). A nonspecific term referring to disease or damage of the kidneys. "Overexpression of KLF4 significantly reduces renal triglyceride deposition, protects against obesity-related nephropathy, and can be used as a prognostic marker to guide clinical evaluation." (PMID 40265156, 2025). "We identified six common target genes associated with renal diseases, and three (HIF1A, FOXO1, KLF4) are related specifically with LN." (PMID 32085620, 2020). "More importantly, clinical renal biopsies further confirmed the close correlation between renal KLF4 levels and renal function, which supported the prognostic ability of KLF4 in kidney diseases." (PMID 31800161, 2020). "Although several KLF members including KLF2, KLF4, KLF6, and KLF15 in glomerular endothelial cells or podocytes have been linked to kidney diseases, all these reported KLF members serve as renal protectors." (PMID 30948420, 2019).
renal carcinoma (7 papers, 2011 to 2025). A carcinoma arising from the epithelium of the renal parenchyma or the renal pelvis. "In contrast to a previous report that KLF4 inhibits both migration and invasion in renal cancer cells, over-expression of KLF4 significantly promoted cell migration in the scratch assay and transwell migration assay compared with the control cells (P < 0.01)." (PMID 26517087, 2015). "Consistently, a DNA methyltransferase inhibitor increased KLF4 expression in renal cancers." (PMID 34680284, 2021). "Both KLF4 and EVI2B were identified by the Human Protein Atlas as markers for renal cancer prognoses (favorable and unfavorable, respectively)." (PMID 34108011, 2021). "Especially, the expression of c-MYC, KLF4, OCT4, NANOG and SOX2 implies that these 5 factors are involved in carcinogenesis and progression of RCC, and probably there are RCC cancer stem cells existing in renal carcinoma." (PMID 21982273, 2011).
rheumatoid arthritis (7 papers, 2018 to 2025). A chronic, systemic autoimmune disorder characterized by inflammation in the synovial membranes and articular surfaces. "Interestingly, a study on rheumatoid arthritis revealed that overexpression of KLF4 in macrophages led to an M1 phenotype, characterized by elevated inflammatory cytokine production." (PMID 40640934, 2025). "Indeed, elevated expression of KLF4 has been reported in synovial tissue from rheumatoid arthritis patients and in the epidermis of psoriatic skin, but the exact role of KLF4 in the pathogenesis of these inflammatory diseases remains to be defined." (PMID 31805013, 2020). "IPA of annotated transcripts showed similar activation of osteogenic-associated pathways such as roles of osteoblasts, osteoclasts, and chondrocytes in rheumatoid arthritis as well as the expression of typical osteogenic genes such as dlx5, tsc22d3, alpl, klf4, ext1, and stc1 in both datasets." (PMID 30376879, 2018). "This study aimed to reveal the mechanism of transcription factor Kruppel-like factor 4 (KLF4) in regulating M1 polarization of macrophages in rheumatoid arthritis (RA) in order to induce inflammatory response." (PMID 35748767, 2022). "Another gene in the same locus as CTNNAL1 is KLF4, which has been found to interact with TNF-α in rheumatoid arthritis." (PMID 31031798, 2019).
acute kidney injury (6 papers, 2020 to 2025). Sudden and sustained deterioration of the kidney function characterized by decreased glomerular filtration rate, increased serum creatinine or oliguria. "Endothelial KLF4 has a renoprotective effect against acute kidney injury and KLF4 in podocyte-suppressed proteinuria." (PMID 35269384, 2022). "Several studies have demonstrated Kruppel‐like factor 4 (KLF4) participated in renal dysfunction and structural disorders in acute kidney injuries, but whether it affected the process of chronic kidney diseases was unknown." (PMID 31800161, 2020). "Recent evidence has shown that endothelial KLF4 is renoprotective and mediates statin-induced protection against ischemic acute kidney injury (AKI) by regulating the expression of CAMs and concomitant recruitment of inflammatory cells." (PMID 32264912, 2020). "Targeting the KLF4/Galectin-3 axis with Kenpaullone and GB1107 confirmed protective effects against cisplatin-induced cell death and acute kidney injury, respectively." (PMID 41079936, 2025). "Previous study has demonstrated renal endothelial KLF4 was involved in the process of acute kidney injury, but no report determined the possible role of KLF4 in chronic renal diseases." (PMID 31800161, 2020). "Regarding the kidney, recent studies showed that KLF2, KLF4, KLF5, KLF6, and KLF15 were distributed in glomeruli and renal tubules and played important roles in the occurrence and development of proteinuric glomerular diseases and acute kidney injury 28-32,53,54." (PMID 36632460, 2023).
cardiomyopathy (6 papers, 2017 to 2024). A disease of the heart muscle or myocardium proper. "For instance, it is unclear whether KLF2 and KLF4 participate in gestational diabetes mellitus-associated cardiomyopathy." (PMID 38516000, 2024). "However, Yoshioka and Dowdy also successfully generated iPSCs from adult human fibroblasts of 54- to 77-year-old healthy donors and from a 24-year-old cardiomyopathy patient using srRNA encoding the reprogramming factors Oct4, Sox2, Klf4, Glis1, and cMyc." (PMID 31320906, 2019). "We found that a single transfection of a five factor (5F) srRNA, containing OCT4, KLF4, SOX2, GLIS1 and c-MYC, robustly generated iPSCs from adult human fibroblasts aged 54 to 77 and from a 24 year old cardiomyopathy patient donor." (PMID 28750082, 2017). "Based on the findings of cell type-specific regulatory activity, the most active TFs in each of the 4 cardiomyopathy fibroblast subpopulations, including NR3C1 (C0 THBS4+ Fibroblasts), KLF4 (C1 LINC01133+ Fibroblasts), FOSB (C2 FGF7+ Fibroblasts), FOS (C3 AGT + Fibroblasts)." (PMID 38799173, 2024). "We found that five factor srRNA (5F-srRNA), including OCT4, KLF4, SOX2, GLIS1 and c-MYC (OKSi-GM), significantly increased iPSC generation in six different adult human fibroblasts, including old adult fibroblasts and a cardiomyopathy patient donor." (PMID 28750082, 2017).
colorectal tumors (6 papers, 2014 to 2023). "Upon loss of KLF4 in the colorectal tumor [SB474T], the levels of the cytoplasmic and nuclear β-catenin are significantly increased while its membranous expression is decreased (P < 0.001)." (PMID 32566755, 2019). "KLF4, a zinc finger transcription factor, regulates the proliferation, migration, invasion, and apoptosis of colorectal tumor cells." (PMID 37636389, 2023). "Taken together this analysis indicates that the tissue remodelling signature in colorectal tumours is in part due to the infiltration of myeloid cells and the KLF4 is the TF sustaining the myeloid state in the infiltrating immune cells." (PMID 30287917, 2018). "We further show that the KLF4 activity score is significantly higher in colorectal tumours with predicted infiltration of cells from the myeloid lineage." (PMID 30287917, 2018). "In this study, we examined the KLF4 mRNA level in colorectal tumors and normal tissues and evaluated the clinical significance of KLF4 expression on prognosis in CRC patients." (PMID 25060774, 2014). "Interestingly, high KLF4 levels in normal tissues surrounding colorectal tumors were found indicative of poor prognosis suggesting that some KLF4 downstream effectors, such as the miR-182 cluster, maybe transferred from normal to tumor cells, thereby contributing to tumor genesis or progression." (PMID 28412746, 2017). "Immunohistochemical analysis showed that KLF4 is significantly downregulated in human colorectal tumors relative to peritumor tissues, exhibiting negative correlation with MEX3A." (PMID 36276637, 2022).
Hodgkins lymphoma (6 papers, 2014 to 2025). A heterogeneous group of malignant lymphoid neoplasms of B-cell origin characterized histologically by the presence of Hodgkin and Reed-Sternberg (HRS) cells in the vast majority of cases. "In Hodgkin’s lymphoma cell lines, KLF4 overexpression resulted in increased apoptosis through the activation of the BAK1 proapoptotic gene." (PMID 40831570, 2025). "It is reported that tucidinostat and decitabine showed a synergistic effect to inhibit cell growth of Hodgkin lymphoma through upregulating the expression of tumor suppressor genes PU.1 and Kruppel-like factor 4 (KLF4)." (PMID 36120308, 2022). "Therefore, we could come to a conclusion that chidamide and decitabine can synergistically induce apoptosis of Hodgkin lymphoma cells by up-regulating the expression of PU.1 and KLF4." (PMID 29100410, 2017).
ischemic stroke (6 papers, 2015 to 2023). A stroke disorder caused by obstruction of blood flow to the brain, due to thrombotic (local blood clot formation) or embolic (due to a blood clot or other material traveling from another site) event. "In a recent study, Wang and Li suggested the critical role of KLF4 in regulating the activation of A1/A2 reactive astrocytes following ischemic stroke." (PMID 37510352, 2023). "To confirm this, in the current study, we used dual IF staining to reveal their intrinsic relationship between the expression of astrocytic C3 and KLF4 following ischemic stroke." (PMID 36823628, 2023). "We also showed that astrocyte-derived KLF4 has a critical role in regulating the activation of A1/A2 reactive astrocytes following ischemic stroke by modulating expressions of NF-κB." (PMID 36823628, 2023). "Previously, anti-inflammation Krüppel-like factor 4 (KLF4) encoded by the Klf4 gene was found to relieve cerebral vascular injuries by improving vascular endothelial inflammation and regulating the expression of tight-junction proteins after ischemic stroke." (PMID 37510352, 2023). "Moreover, KLF4 can alleviate cerebral vascular injury by ameliorating vascular endothelial inflammation and regulating tight junction protein expression following ischemic stroke." (PMID 36823628, 2023). "In the current study, we found that the expression of S100A10 in astrocyte decreased at day 2 post-ischemia, but then increased by 4–14-day post-ischemia, peaking at day 7, and declining at day 14, and this is almost identical to the dynamic changes of KLF4 in astrocytes following ischemic stroke." (PMID 36823628, 2023). "We provide evidence that serum levels of CAMs and KLF4 mirror the severity of ischemic stroke." (PMID 32264912, 2020). "Importantly, KLF4 can protect brain microvascular endothelial cells from ischemic stroke-induced apoptosis." (PMID 32264912, 2020). "This suggests that OGD is a positive factor for inducing Klf4 following ischemic stroke in vivo." (PMID 25945100, 2015). "Interestingly, the dual IF staining showed that where the high levels of KLF4 were expressed, relatively low levels of CAMs were expressed on the cerebral blood vessels in the ischemic hemisphere during the early stage (at day 2) of ischemic stroke, and vice versa." (PMID 32264912, 2020). "In the next set of experiments, we will directly test whether KLF4 alleviates cerebral vascular injury after ischemic stroke by using mice lacking or overexpressing KLF4 in endothelial cells." (PMID 32264912, 2020). "In addition, we found that Sox2 expression by OGD treatment was not as remarkable as Klf4 expression, although Sox2 was activated in iSCs following ischemic stroke." (PMID 25945100, 2015).
oesophageal cancer (6 papers, 2012 to 2023). "Conversely, upregulation of KLF4 was associated with inflammation and esophageal carcinoma formation, while miR-7 could inhibit the migration and invasion of ESCC through downregulation of KLF4." (PMID 37031197, 2023).
pancreatic ductal carcinoma (6 papers, 2011 to 2024). "It has been reported that Krüppel-like factor 4 (KLF4) transcriptionally inhibits MSI2 expression by directly binding to the MSI2 promoter in multiple pancreatic ductal adenocarcinoma (PDAC) cell lines." (PMID 33553241, 2020). "As to the function on stems cell or CSCs, recent studies have shown that KLF4, as a negative regulator of CD44, has the function of inhibiting the characteristics of cancer stem cells in pancreatic ductal carcinoma." (PMID 39695175, 2024).
renal cell carcinoma (6 papers, 2014 to 2022). "It has been revealed that CD133, CD24, CD105, Snail, Nanog, Twist, OCT-3/4, CRT2, BCL-2,MDR1, KLF4 and so on are stemness markers in CSCs of renal cell carcinoma or other types of tumor." (PMID 28279221, 2017). "KLF4 was upregulated in osteosarcoma and primary breast ductal carcinoma, but downregulated in lung cancer, gastric cancer, hepatoma, prostate cancer, and renal cell carcinoma suggesting its tumor suppressor role." (PMID 29254226, 2017). "This prompted us to hypothesize that the epigenetic repression of KLF4, similar to its role in renal cell carcinoma, may promote EMT in renal fibrogenesis." (PMID 25892014, 2015). "Moreover, it has been reported that KLF4 is epigenetically silenced by promoter methylation and functions as a tumor suppressor gene in renal cell carcinoma." (PMID 25892014, 2015).
Stroke (6 papers, 2020 to 2025). Sudden impairment of blood flow to a part of the brain due to occlusion or rupture of an artery to the brain. "In stroke models, KLF4 has a protective effect on microvascular ECs." (PMID 39684585, 2024). "In accordance with our infarct core-to-border axis (punch positions 5–8) analysis, we found that seven of the KLF family of TFs (KLF2–4, 6–8, and 12) were significantly depleted in glutamatergic neurons at the glial scar in the stroke hemisphere (KLF4 and KLF7 shown)." (PMID 33627658, 2021). "Furthermore, the serum level of KLF4 was negatively correlated with infarct volume at 48 h after stroke onset in all the CIS subjects." (PMID 32264912, 2020). "Moreover, the expression of EndoMT markers KLF4 and α-SMA increased in ECs until RP8D and decreased at RP34D after stroke." (PMID 40667795, 2025).
teratoma (6 papers, 2014 to 2023). A non-seminomatous germ cell tumor characterized by the presence of various tissues which correspond to the different germinal layers (endoderm, mesoderm, and ectoderm). "In the present study, our finding indicated that, transfection with Oct4/Sox2/Klf4/Parp1(OSKP) were capable of the generation of OSKP-iPSCs that formed smaller teratoma than iPSCs reprogrammed with the conventional reprogramming factors Oct4/Sox2/Klf4/c-Myc." (PMID 29719629, 2018). "We also confirmed that all the patient-derived iPSC lines expressed the embryonic stem cell markers OCT3/4, SOX2, NANOG, REX1, MYC, and KLF4 and were capable of forming teratomas." (PMID 29088246, 2017). "As Klf4 is a proto-oncogene, reactivation of the transgene could lead to the formation of teratomas and possibly other types of tumors, when transplanted." (PMID 27275539, 2016). "In addition, these models utilize transduction of fibroblast with retroviruses encoding OCT4, SOX2, KLF4 and c-MYC, which are by and large cancerous and form teratomas." (PMID 25140287, 2014).
urothelial bladder cancer (6 papers, 2017 to 2025). "Researchers used the CRISPR-ON method to upregulate KLF4 expression in a study, which looked at the effect and mechanism of KLF4 in the carcinogenesis and development of urothelial bladder cancer (UBC)." (PMID 35331236, 2022). "For example, overexpression of KLF4 in T24 urothelial bladder carcinoma cells leads to p21 accumulation, G1-phase arrest, and a significant decrease of tumor growth in a xenograft model." (PMID 33640491, 2021). "In the present study, we utilized the CRISPR-ON system to upregulate KLF4 expression level and subsequently investigated the effect and mechanism of KLF4 in the carcinogenesis and progression of urothelial bladder cancer (UBC)." (PMID 29254226, 2017). "Additionally, KLF4 has been identified as a prognostic predictor for urothelial carcinoma of the bladder, where it regulates TWIST1-mediated epithelial-mesenchymal transition." (PMID 40299916, 2025).
adenoma (5 papers, 2009 to 2025). A neoplasm arising from the epithelium. "For instance, KLF4 expression seems to be higher in normal colon mucosa while it decreases during the adenoma–carcinoma progression of CRC." (PMID 40863723, 2025). "These recent data are therefore consistent with the previous research supporting the tumor-suppressive role of KLF4 in the adenoma–carcinoma progression of CRC." (PMID 40863723, 2025). "In familial adenomatous polyposis (FAP) patients, KLF4 transcript level is lower in adenomas compared to paired normal-appearing mucosa." (PMID 20119532, 2009).
asthma (5 papers, 2020 to 2024). "In line with previous study, our study also found that KLF4 is significantly associated with asthma severity and lung function." (PMID 38245772, 2024). "In addition, we found hypo-methylated KLF4 significantly associated with asthma severity and lung function, which suggests that methylation effect may regulate KLF4 in asthma and lung function disease development." (PMID 38245772, 2024). "The important regulators of ASMCs, miR-25 and -145, are involved in the pathogenesis of asthma by targeting Krüppel-like factor 4 (KLF4)." (PMID 34635022, 2021). "At the cellular level, human ASM cells treated with TNF-α, IL-1β, and IFN-γ (imitate the inflammatory conditions in patients with asthma) induced an up-regulation of miR-145-5p and a down-regulation of Krüppel-like factor 4 (KLF4), an inhibitor of smooth muscle cell proliferation." (PMID 38337625, 2024). "The same study showed that the negative regulation of KLF4 by overexpression of miR-145-5p enhanced the proliferation and migration of ASM cells in vitro, suggesting that this miRNA may participate in the smooth muscle remodeling present in asthma pathology." (PMID 38337625, 2024).